PAX5 (paired box 5)
Diseases named in the same sentence as PAX5 in open-access papers (continued):
Sharing a sentence is not in itself a finding about the gene and the disease.
tumor (continued). "Tissue microarray contains GBC tumour tissues was used to evaluate the association between the expression of ELP5, DNMT3A and PAX5." (PMID 34823564, 2021). "The tumor suppressor role of Pax5 has been revealed in these mice using chemical-induced mutagenesis approaches." (PMID 34771671, 2021). "In conclusion, the fusion resulted in partial oncogenic activity, in contrast to the tumor suppressor activity of wild-type PAX5." (PMID 34513684, 2021). "Overexpression of miR-1254 in tumor tissues led to less expression of PAX5 but more of Ki-67, while knockdown of miR-1254 led to the reverse result compared with controls." (PMID 33403035, 2021). "circMALAT1 is highly expressed in cancer stem cells (CSCs), where it constitutes a ternary complex with the mRNA of paired box 5 (PAX5), a tumor suppressor, and ribosomes." (PMID 34202482, 2021). "Tight regulation of PAX5 levels is critical for normal B-cell lymphopoiesis but also to prevent tumor development." (PMID 34210001, 2021). "PAX5 was reported to act as a tumor suppressor in HCC 35, so we were interested in PAX5 among the screened candidates." (PMID 33403035, 2021). "Combining with all experimental data above, PAX5-activated IDH1-AS1 acted as an oncogene in PCa tumor growth by promoting ATG5-induced autophagy." (PMID 31570703, 2019). "Then these two types of tumor tissues and their 2D and 3D cultures were investigated for changes considering methylation levels in PAX5, TMPRSS2, and SBDS genes using real-time polymerase chain reaction." (PMID 30792990, 2019). "Due to variable cellular composition and challenging morphological assessment of the polymorphic infiltrates, PD‐L1 positivity of tumor cells was confirmed by double PAX5/PD‐L1 staining in the latter." (PMID 31269329, 2019). "Collectively, the focus of this study is on exploring the role of PAX5-activated IDH1-AS1 in PCa tumor growth via ATG5-induced autophagy." (PMID 31570703, 2019). "Δ3C virus-infected and WT virus-infected tumors expressed very similar levels of PAX5, suggesting a similar number of B cells in each tumor sample." (PMID 30125329, 2018). "The substantial increase in tumor incidence in CaStat5 mice as a result of Ebf1- or Pax5-haploinsufficiency underscores the importance of these transcription factors in maintaining cellular differentiation despite strong oncogenic signaling." (PMID 28692033, 2017). "Deletion of IKZF1 is associated with particularly poor clinical outcomes, and recent studies based on a PAX5 restoration model clearly validated the powerful tumor-suppressive function of PAX5 in B lineage ALL." (PMID 28199841, 2017). "CHL tumor cells were positive for PAX5 (10/12, 83.3%), CD30 (12/12, 100%), CD15 (9/12, 75.0%), CD20 (4/12, 33.3%) and CD79a (2/9, 22.2%)." (PMID 28566711, 2017). "To elucidate the downstream signalling pathways mediated by PAX5 in tumour inhibition, we performed semi‐quantitative PCR and Western blot to evaluate the expression of components of the β‐catenin signalling pathways." (PMID 26843424, 2016). "Expression of PAX5 protein in isolated tumour tissues was confirmed by immunohistochemical staining of PAX5 monoclonal antibody in the nucleus and by western blot." (PMID 26843424, 2016). "In primary NSCLC tissues, adjacent non‐tumour tissues and normal lung tissues, the methylation frequencies of PAX5 promoter were 70% (33/47), 73% (29/40) and 13% (2/16), respectively." (PMID 26843424, 2016). "Our data suggest that PAX5 functions as a transcription factor of YMO1, further supporting a tumor suppressor role of PAX5." (PMID 27487132, 2016).
tumor (continued). "Our results strongly suggest PAX5 as a novel functional tumour suppressor that is inactivated by epigenetic regulation in NSCLC." (PMID 26843424, 2016). "Recent studies suggest that paired box 5 (PAX5) is down‐regulated in multiple tumours through its promoter methylation." (PMID 26843424, 2016). "And for the first time, we provided evidence of PAX5 acting as a tumour suppressor in NSCLC from biological function and molecular levels, thus laid the groundwork for potential clinical application." (PMID 26843424, 2016). "Frequent PAX5 promoter methylation in primary tumours (70%) was correlated with lung tumour histological types (P = 0.006)." (PMID 26843424, 2016). "The diminution of tumour growth by PAX5 re‐expression was also detected by xenografted tumour formation in nude mice." (PMID 26843424, 2016). "PAX5 is also one of factors inversely correlated with tumor nodule number, capsule formation, vascular invasion and TNM Stage." (PMID 27487132, 2016). "In summary, PAX5 was found to be an epigenetically inactivated tumour suppressor that inhibits NSCLC cell proliferation and metastasis, through down‐regulating the β‐catenin pathway and up‐regulating GADD45G expression." (PMID 26843424, 2016). "The mean weight of tumours formed by PAX5‐transfected cells was significantly lower than that of vector control formed tumours (P < 0.05), indicating that PAX5 can inhibit NSCLC cell grow tumours in vivo." (PMID 26843424, 2016). "Its role as a tumour suppressor in leukaemogenesis has recently gained prominence in that PAX5 inactivation has been shown to be one of the most common genetic alterations in pre‐B ALL and results in a reversible differentiation block." (PMID 26310606, 2015). "We based this on Ig clonality, uniform cytogenetic features throughout the tumor, and the shared expression of PAX-5." (PMID 23738160, 2013). "It is well established that cHL is a neoplasm of germinal center B-cell derivation due to the demonstration of weak Pax-5 expression by HRS cells by immunohistochemistry." (PMID 22967962, 2012). "Pax5 is inactivated by aberrant methylation in tumor cell lines, as well as primary tumors from breast and lung." (PMID 19703295, 2009). "Notably, Pax5 also contributes to B-cell activation and is expressed in tumor-infiltrating B cells within the TME, suggesting functional relevance in shaping anti-cancer immunity." (PMID 41471367, 2025). "B cell markers (CD20, CD79a, and PAX-5) were positive in the tumor cells." (PMID 40933576, 2025). "Analysis of the FAH-SYSU cohort revealed that the expression level of PAX5 was higher in tumor tissues and, to some extent, could predict OS and DFS in patients with ccRCC." (PMID 38926764, 2024). "Because Pax5 is a haploinsufficient tumor suppressor in human B-ALL8,10, we investigated whether the SIRT7–PAX5 interplay was functionally relevant in this disease." (PMID 39424985, 2024). "Furthermore, PAX5 functioned as a tumor suppressor by directly regulating miR-142-5p/3p by experiments both in vitro and in vivo." (PMID 37403081, 2023). "Pax5 is also expressed by infiltrating leukocytes surrounding the tumor." (PMID 38168280, 2023). "PAX5 is frequently downregulated in HL, thus inhibiting B-cell differentiation in the tumor cells." (PMID 35884913, 2022). "Immunohistochemistry showed that the tumor cells were CD79a+, PAX-5+, MUM1+, and CD20-." (PMID 36581860, 2022). "Pax5 was expressed in scattered cells in the lamina propria, especially in the tumor periphery." (PMID 35448666, 2022). "Hence, Pax5 maintains B cell identity throughout B‐lymphopoiesis and functions as a tumor suppressor in the B‐lymphoid lineage." (PMID 35156727, 2022).
tumor (continued). "Hence, tumor development is initiated in committed B cells, but then leads to dedifferentiation of the Pax5Jak2/+ B‐ALL cells due to the loss of Pax5 function similar to what is observed upon conditional Pax5 deletion in pro‐B cells." (PMID 35156727, 2022). "Moreover, we found that the expression level of CD81 was positively correlated with Pax5 expression in human tumor cell lines." (PMID 34824296, 2021). "Expression of PAX5 and Ki-67 in tumor tissues was detected by immunohistochemistry." (PMID 33403035, 2021). "All these studies indicate that the anti-tumor activity of PAX5 in HCC may involve more mechanisms, to be studied in the future." (PMID 33403035, 2021). "Lower PAX5 expression was detected in tumor tissues than in peritumor tissues by IHC analysis." (PMID 33403035, 2021). "In addition, the Pax5 tumor-suppressor activity has been demonstrated through the modulation of other critical transcription factors, such as Ebf1, Ikzf1 and Stat5." (PMID 34771671, 2021). "Lack or inactivation of PAX5 results in tumour progression and promotes a malignant state." (PMID 34823564, 2021). "In addition, the fusion showed partial oncogenic activity, which was in contrast with the tumor suppressor ability of wild-type (WT) PAX5." (PMID 34513684, 2021). "CD20, CD79a, PAX5 which were markers of B lymphocyte was strong in almost 90% of tumor nuclei." (PMID 33585230, 2020). "Interestingly, two PAX motifs, PAX5 (tumor suppressive) and PAX6 (oncogenic), were frequently found in hyper- and hypomethylated intron DMRs, respectively." (PMID 32693820, 2020). "We could identify between 8 and 58 somatic single-nucleotide variations (SNVs) in the tumor samples of Pax5-het/Aid-het mice and between 11 and 27 somatic SNVs in the tumor samples of Pax5-het/Aid-KO mice." (PMID 31804490, 2019). "The primary objective of our study is to determine whether primary tumor tissue and cultured tumor cells in 2D and 3D tissue culture systems have the same methylation signature for PAX5, TMPRSS2, and SBDS." (PMID 30792990, 2019). "No study was reported about PAX5 haploinsufficiency involved in immune tolerance, but we had evidence to assume that PAX5 haploinsufficiency may result in tumor immune tolerance." (PMID 28316978, 2017). "Moreover, Pax5 modulates the transcription of genes involved in the migration and adhesion of B cells, and promotes the adhesion of intercellular junctions in tumor cells." (PMID 28900388, 2017). "Similarly, PAX5 proteins are thought to possibly inhibit tumor cell apoptosis, augmenting tumorigenesis." (PMID 28574840, 2017). "BACH2 is a tumor suppressor and it is reported to be frequently inactivated in primary pre-B ALL patients via promoter hyper-methylation, missense mutations and deletions, as well as via loss of its upstream regulator paired box 5 (PAX5)." (PMID 28030830, 2017). "The ability to suppress proliferation implies that PAX5 is a potential tumour suppressor in NSCLC." (PMID 26843424, 2016). "Of note, this patient’s tumor also possessed likely deleterious alterations in PAX5 and SETD2." (PMID 27974047, 2016). "Moreover, real‐time PCR results showed that PAX5 expression was down‐regulated in 83% (19/23) of primary NSCLC tumour tissues compared with their corresponding adjacent tissues (P < 0.0001)." (PMID 26843424, 2016). "H1975 cells stably transfected with PAX5 or empty vector formed tumours in nude mice." (PMID 26843424, 2016). "That is to say, patients with primary tumor located in lower third stomach should detect the methylated statuses of CpG sites of PAX5 promoter, especially in the CpG sites (-236, -183, -162, and -152), for contribution to enhancement the precise efficiency of the prognostic evaluation." (PMID 25277182, 2014). "Other researchers demonstrated that the low or loss expression of PAX5 was detected in the human cancers, which indicates PAX5 may function as a potential tumor suppressor in the carcinogenesis." (PMID 25277182, 2014).
tumor (continued). "Finally, we found that only primary tumor location was correlated to the methylated statuses of CpG sites of PAX5 promoter." (PMID 25277182, 2014). "Additionally, IL-35/STAT3/PAX5/BCL6 signaling-driven transcriptional dysregulation in naïve B cells could impair their differentiation into anti-tumor effector cells." (PMID 41522514, 2026). "Similarly to other neoplasms with plasmablastic differentiation, ALK+ LBCLs express plasma cell-associated markers (CD138, CD38, MUM1/IRF4 and BLIMP1) and are negative or only weakly positive for mature B-cell markers (CD20, CD19, PAX5 and CD79alpha)." (PMID 40869163, 2025). "PAX5 typically involved in B‐cell lineage commitment, but its aberrant expression in NB may point to ectopic activation of lineage‐inappropriate programs, possibly influencing immune‐related gene expression or tumor plasticity." (PMID 40600620, 2025). "However, circMALAT1 (hsa_circ_0002082) acts as a proto-oncogene or tumor-suppressor gene, and circMALAT1 can inhibit the translation of the tumor-suppressor gene PAX5 and also act as a sponge of miR-6887-3p, activate the JAK/STAT3 signaling pathway and promote the self-renewal of cancer stem cells." (PMID 36006268, 2022). "Therefore, we thought that PAX5 functioned as a tumor suppressor gene in GC." (PMID 25277182, 2014). "All neoplasms labeled positively for MUM-1, negatively for PAX5, and were variably CD20- and CD79b-positive." (PMID 40215400, 2025). "Bone marrow biopsy revealed the presence of tumor cells, and immunohistochemical staining showed that the tumor cells were positive for CD34, MPO, and CD99, and weakly positive for PAX-5, suggesting a diagnosis of AML." (PMID 41561755, 2025). "Diagnosis is primarily cytological, hinging on the classic “starry sky” appearance, alongside immunophenotyping that shows tumor cells positive for B‐cell markers (CD19, CD20, CD22, CD79a, CD38, PAX5) and germinal‐center markers (CD10, BCL6)." (PMID 40951226, 2025). "Immunohistochemical (IHC) studies of the bone trabeculae showed the intact structure, and the tumor cells exhibited strong diffuse positivity for CD20, CD79a, Pax-5, CD10, and BCL-2." (PMID 40746899, 2025). "PAX genes from subgroups II (PAX2, PAX5, and PAX8) and III (PAX3 and PAX7) are involved in essential processes such as cell survival, motility, and tumor progression." (PMID 40506992, 2025). "The tumor cells in PBL express plasma cell markers, such as CD38 and CD138, and frequently lack the traditional B-cell markers, namely, CD20 and PAX5." (PMID 41497913, 2025). "In the MBNL1/circNTRK2/PAX5 pathway, the transcription factor PAX5, which is highly expressed in GBM, directly binds to the PKM2 promoter, increasing its transcription and protein expression, thereby sustaining tumor glycolysis and progression." (PMID 41169372, 2025). "B-ALL is a neoplasm of precursor lymphoid cells committed to the B-cell lineage, characterized by the expression of CD19, CD22, cytoplasmic CD79a, and/or PAX5, as determined by flow cytometry or immunohistochemistry." (PMID 41333696, 2025). "Immunophenotypically, the tumor cells exhibit a mature germinal center B-cell profile, with positivity for CD19, CD20, CD79α, PAX5, CD10, and BCL6, and negativity for CD5 and TdT." (PMID 41561748, 2025). "Immunohistochemistry and in situ hybridization analyses demonstrated tumor cells positive for cluster of differentiation 20 (CD20), CD19, paired box 5 (PAX5), CD10, B cell lymphoma 6 (Bcl6), and Bcl2 (approximately 80%)." (PMID 39891266, 2025). "The tumor showed strong expression of CD20, CD79a, PAX5, and Ki-67 (close to 90%), but CD3, CD56, and TIA1 were all negative." (PMID 41291370, 2025).
tumor (continued). "Usually, when analyzing the tumor genome by CMA, aberrations larger than 5 MB and additional microdeletions involving the CDKN2A/B, BTG1, EBF1, ETV6, ERG, IKZF1, PAX5, and RB1 genes are taken into account." (PMID 39408811, 2024). "All these genes are either involved in the regulation of MAPK and PI3K/AKT signaling pathways in addition to serving as tumor suppressors affecting drug resistance in other cancers including Homeobox protein Hox-D8 (HOXD8) and Paired Box 5 (PAX5)." (PMID 38275910, 2024). "Histologically, tumor cells conform to mature B cells (late germinal center exit), and thus they express typical mature B cell markers such as CD20, CD19, PAX5, or CD79a." (PMID 37872367, 2023). "Most of these genes are reported to be involved in either lymphoid development (such as PAX5 and IKZF1), lymphoid signaling, cell cycle and apoptosis regulation (mostly tumor suppressors such as CDKN2A), DNA repair, therapy response, or transcription factors." (PMID 36980958, 2023). "mmunohistochemical staining showed that the tumor cells were positive for CD20, CD79a, PAX-5, Bcl6, MUM-1, CD19, c-Myc (Y69) (40%), and Bcl2 (80%)." (PMID 37884941, 2023). "These included genes consistent with pro-inflammatory immune responses (CD27, CD28, CD3e, CD8a, ICOS, ICOSLG, Pax5, TBX, GATA3, HLA-A, TNFSF14, GPR146), but also immune suppressive influences in the tumor immune microenvironment (CTLA-4, FoxP3, PD-1)." (PMID 36698398, 2022). "For example, PAX genes in subgroups II (PAX2, PAX5, and PAX8) and III (PAX3 and PAX7) are commonly involved in processes including cell survival, motility, and tumor progression." (PMID 36077495, 2022). "Immunohistochemically, tumor cells had an intact B-cell phenotype with the expression of CD20, CD79a and PAX5." (PMID 36606194, 2022). "Immunofluorescence (IF) staining was performed on whole tumor sections and stained for CD3, CD8, PNAd, Pax5, and CD11b." (PMID 34253827, 2021). "To corroborate this hypothesis, we tested whether the heterozygous loss of Pax5 (Pax5-het), a common second hit identified in murine and human B-ALL-associated ETV6-RUNX1, would restrict the tumor cell type to B-ALL in Sca1-ETV6-RUNX1 mice, similarly to Kdm5c loss." (PMID 34336858, 2021). "The tumor was immunonegative for CD3, CD20, PAX5, MUM1, pan-cytokeratin, S100, NSE, p75NTR, NeuN and periaxin." (PMID 34977226, 2021). "Thus, based on the results of this study, we could determine the transcriptional regulatory pattern between LTB and PAX5 and their cellular colocalization in cancer cells, and whether this regulatory mechanism existed in tumour-infiltrating B cells and plasma cells needs to be further validated." (PMID 33397394, 2021). "In each gene of the panel, Tumor QMSP was significantly higher than normal QMSP (CD1D: p < 0.001, KCNK12: p < 0.001, PAX5: p < 0.001)." (PMID 34530906, 2021). "In this study, we identified PAX5 and PAX6 motifs, known to be tumor suppressive and oncogenic TFs that are enriched in hyper- and hypomethylated intron DMRs of CMT, respectively." (PMID 32693820, 2020). "The expression level and in situ localization of miR-18a and -18b was assessed with respect to the presence of tumour infiltrating lymphocytes (TILs) and immunohistochemical markers for ER, CD4, CD8, CD20, CD68, CD138, PAX5 and actin." (PMID 32370743, 2020). "We indeed focused on two PAX motifs, PAX5 and PAX6 that have been known as tumor suppressive and oncogenic, respectively." (PMID 32693820, 2020). "In terms of pathological diagnosis, the immunophenotype analysis showed that the stromal lymphocytes were positive for CD20, CD79a, and BCL-2, while the tumor cells were positive for BCL-10, NF-kB, p65 and PAX-5." (PMID 33585230, 2020). "Based on these results, we defined a tumor-induced plasmablast-like-enriched B cell population (TIPB) signature with the genes CD27, CD38, and PAX5." (PMID 31519915, 2019).